TNF (tumor necrosis factor)
Diseases named in the same sentence as TNF in open-access papers (continued):
Sharing a sentence is not in itself a finding about the gene and the disease.
Obesity (continued). "It suppresses the production of pro-inflammatory cytokines, such as TNF-α and IL-6, thereby mitigating chronic low-grade inflammation associated with obesity." (PMID 38255203, 2024). "In a mice model of diet-induced obesity, inhibiting TNF-α inhibits the development of obesity-associated insulin resistance, highlighting the importance of pro-inflammatory variables in the etiology of type 2 diabetes." (PMID 39513912, 2024). "The hyperplasia andhypertrophy of adipose tissues caused by obesity are often driven by theexcessive release of pro-inflammatory cytokines from these tissues, known asadipokines, including TNF-α, IL-6, and interleukin-3 (IL-3)." (PMID 39742220, 2024). "Obesity-related inflammation is linked to pro-inflammatory cytokines such as TNF-α, IL-6, uric acid, and CRP, which interfere with normal GnRH secretion from the hypothalamus and reduce testosterone production." (PMID 39473678, 2024). "Higher expression levels of CXCL1 and CXCL8 were identified as independent risk factors for significant weight gain, and CXCL1 and TNF were identified as independent risk factors for new-onset postoperative obesity." (PMID 38965454, 2024). "Chronic low-grade inflammation, characterized by elevated levels of pro-inflammatory cytokines such as TNF-α, IL-6, and IL-1β, is a hallmark of obesity and insulin resistance." (PMID 38920999, 2024). "Current data demonstrated a significant positive correlation of asprosin and TNF- α, as a pro-inflammatory indictor associated with obesity, with a Fisher’s Z of 0.39 (95% CI: 0.07 to 0.71, p = 0.02)." (PMID 38475734, 2024). "Insulin resistance and adipocyte proliferation caused by obesity lead to the secretion of inflammatory mediators by adipocytes, such as Interleukin-6 (IL-6), Tumor Necrosis Factor-alpha (TNF-α), and C-reactive protein (CRP)." (PMID 38933362, 2024). "Another mechanism underlying low iron levels in obesity is chronic inflammation; adipose tissue secretes multiple pro-inflammatory cytokines including tumor necrosis factor (TNF)-α and interleukin-6 (IL-6)." (PMID 38672754, 2024). "Obesity is associated with inflammation and elevated cytokines such as TNF-α and IL-6, which can lead to tissue damage and contribute to conditions like NAFLD." (PMID 39202687, 2024). "Probiotic treatment effectively prevents obesity or improve obesity-related insulin resistance which was partly associated with reducing TNF-α levels." (PMID 38504163, 2024). "VAT metaflammation in obesity, as measured by mRNA levels of TNF-α, IL6, and MCP-1/CCL2, is associated with insulin resistance and cellular senescence." (PMID 39063184, 2024). "LPS and TNF-α inhibited adipose tissue browning, causing a decrease in energy expenditure and indirectly leading to obesity and related metabolic diseases." (PMID 39050639, 2024). "In people with inflammatory arthritis, systematic reviews also demonstrate that obesity is associated with a reduced likelihood of achieving remission/minimal disease activity and responding to anti-TNF therapy." (PMID 39006539, 2024). "TNF-α is frequently elevated in obesity and often reduced after weight loss in patients without rheumatic disease." (PMID 37501212, 2023). "The elevation of TNF-α and IL-6 due to obesity causes a decrease in glucose transfer protein type 4 (GLUT4) and lower adiponectin levels." (PMID 37367060, 2023). "Our results suggest that, in the context of obesity-associated inflammation, in vitro exposure of HeLa cells to TNF-α increased stemness markers." (PMID 36674737, 2023). "Through its downstream effects on NF‐κB signaling, the overabundance of TNF‐α in these tissues contributes to the disturbances in cell viability, inflammation, and metabolism that underlie obesity." (PMID 38107091, 2023). "Systemic inflammatory factor (TNF-α) and resistin were indicated to be associated with sarcopenia and obesity in a previous study." (PMID 37853348, 2023).
Obesity (continued). "Tumor necrosis factor-α (TNF-α) is another key adipocytokine implicated in the development of insulin resistance in obesity." (PMID 37576807, 2023). "Increased tumor necrosis factor-alpha expression in obesity is associated with the onset of insulin resistance and reduced glucose uptake and utilization in tissues." (PMID 38259415, 2023). "Obesity-associated pro-inflammatory molecules such as saturated fatty acids (sFFAs), tumor necrosis factor (TNFα), and advanced glycated end products (AGEs) activate microglia in the hypothalamus." (PMID 36829858, 2023). "This protection was accompanied by lower macrophage counts in WAT and serum tumor TNF-α levels, which reflect a marked decrease in the local and systemic inflammation linked to obesity." (PMID 37153549, 2023). "High levels of Deferribacteres are often related to obesity, which is positively linked with the pro-inflammatory factors, IL-6, IL-17A, and TNF-α, causing the aggravation of inflammation in obesity." (PMID 37376017, 2023). "In fact, in adipose tissue, the M1 macrophages secrete high levels of pro-inflammatory cytokines (TNF-α, IL-6 and IL-1β), inducing an inflammation state and an impairment of insulin sensitivity, typically associated with obesity." (PMID 37447161, 2023). "Strong evidence has underlined that obesity is characterized by increased blood proinflammatory cytokines (such as IL-1, IL-6, TNF-alpha) and oxidative stress activity." (PMID 37511687, 2023). "Secondly, since obesity causes a low-grade inflammatory state, a higher production of IL-6, adiponectin, leptin, or TNF-α is present." (PMID 38068717, 2023). "Adipose tissue remodeling associated with obesity alters the synthesis of adipokines such as tumor necrosis factor (TNF-α), leptin, and adiponectin." (PMID 36991247, 2023). "Chronic inflammation has been linked to obesity in many different rodent models, with elevated TNF-α expression being shown in the adipose tissue (AT) of obese animals, which can be a mediator of insulin resistance (IR)." (PMID 37241120, 2023). "Inflammatory markers, such as hs-CRP, IL-6, and TNF-α-R2 levels in the blood, were negatively correlated with dietary fibre intake by reducing body weight or limiting obesity-associated systemic inflammation." (PMID 37764817, 2023). "The prevalence of obesity is increasing rapidly worldwide, causing susceptibility to pro-inflammatory state by increasing inflammatory mediators, such as Tumor Necrosis Factor-alpha (TNFα), and Interleukin-6 (IL-6), and reducing the level of adiponectin." (PMID 37246210, 2023). "Obesity results in a low-grade chronic systemic inflammation associated with increases in two inflammatory mediators, IL-6 and TNF-α." (PMID 36986146, 2023). "Mounting studies have demonstrated that macrophages are recruited into adipose tissue and secrete inflammatory cytokines such as IL-1β and TNF-α during obesity, thereby causing local and systemic inflammation." (PMID 38070059, 2023). "The development of IR caused by obesity is connected to the hormones and cytokines produced by adipocytes, including the rise of free fatty acids, TNF, leptin, resistin, and the inadequacy of adiponectin." (PMID 38045856, 2023). "Obesity creates a proinflammatory environment characterized by high levels of circulating interleukin-6, tumor necrosis factor-α, C-reactive protein, and a relative deficiency of protective immune cell types." (PMID 37901321, 2023). "The intracellular contents released by accumulated ACs further trigger an immune response and lead to a release of inflammatory factors, such as TNF-α, IL-1β, and IL-6, which induce the dysfunction of chondrocyte homeostasis in obesity-associated OA." (PMID 37144868, 2023). "In conclusion, our study introduced for the first time a negative association of IL-6 with self-esteem and a positive one of TNF-α with depression in a Greek cohort with obesity." (PMID 37529617, 2023).
Obesity (continued). "Elevated levels of inflammatory markers such as high-sensitivity C-reactive protein (CRP), or tumor necrosis factor alpha (TNF-α) have been associated with pathogenetic mechanisms of obesity, T2DM and cardiovascular diseases." (PMID 37828090, 2023). "An additional mechanism leading to increased GDM risk involves obesity-related chronic inflammation with increased serum levels of cytokines including BMI (body mass index), tumor necrosis factor alpha (TNFα) and C-reactive protein (CRP)." (PMID 37886954, 2023). "Systemic inflammation is prevalent in obesity, and it is one of the key determinants of failure of anti-TNF agents, with each unit increase in BMI associated with 6.5% of failing therapy." (PMID 37371414, 2023). "We conducted a PubMed search in July 2022 using the search term “spondyloarthritis” alone or in combination with one or more of the following terms: “inflammation”, “cardiovascular risk”, “obesity”, “metabolic syndrome”, “TNF”, “IL-17” and “IL-23”." (PMID 37533855, 2023). "In obesity, expanding adipose tissue secretes proinflammatory adipokines, such as interleukin-6 (IL-6) and TNF-a, which can lead to inflammation and metabolic dysfunction associated with obesity." (PMID 37296584, 2023). "TNF-α is implicated in the state of inflammation and metabolic complications associated with obesity." (PMID 36520252, 2023). "Obesity is associated with low-grade inflammation, characterized by the release of pro-inflammatory cytokines including TNFα, IL-1β, and IL-6." (PMID 37373472, 2023). "The levels of inflammatory cytokines (including TNF-α, IL-1β)—that are parameters associated with obesity—are also related to the severity of depression." (PMID 37049434, 2023). "The reduction of obesity-associated pro-inflammatory mediators (e.g., FFAs, TNFα, resistin, and AGEs), and the improvement in the gut–brain axis represent alternative paths through which regular exercise can mitigate hypothalamic inflammation." (PMID 36829858, 2023). "In fact, it has been proven that mitochondrial dysfunction is directly associated with IR, obesity, and the release of pro-inflammatory cytokines levels like tumor necrosis factor-alpha (TNF-α)." (PMID 37347041, 2023). "For instance, leptin and adiponectin contribute to body weight regulation, while TNF-α, IL-6, and IL-1β are associated with local inflammation resulting from obesity." (PMID 37408757, 2023). "Obesity is often associated with low grade inflammation and elevated levels of various pro-inflammatory factors, including TNFα, IL-6, IL-1β and MCP-16." (PMID 37386070, 2023). "Hypoadiponectinemia in obesity is caused by adipocyte hypoxia, oxidative stress, insulin resistance, and increased pro-inflammatory cytokines such as TNF-α and IL-6." (PMID 37104164, 2023). "In contrast, the intake of both catechin and β-cryptoxanthin significantly decreased the level of cytokines, including TNF-α, associated with M1 macrophages, which increase with obesity." (PMID 37108217, 2023). "During obesity, the production of inflammatory adipokines such as TNF and MCP-1 causes additional macrophages to be recruited to adipose tissue, contributing to the inflammatory milieu." (PMID 37080971, 2023). "Several studies have linked chronic tissue inflammation to these disorders, with tumor necrosis factor-α (TNF-α) levels being increased in adipose tissue in obesity." (PMID 37371762, 2023). "Previous studies supported that proinflammatory cytokines (including TNF and IL-1β) from adipose tissue have been implicated in the association between obesity and osteoarthritis." (PMID 36918849, 2023). "Increased blood TNF-α levels are linked to obesity and insulin resistance, both of which are major contributors of MetS." (PMID 36838411, 2023). "Obesity and age-related increases in inflammatory cytokines (e.g. TNF-α, IL-6, and CRP) cause exacerbated danger-associated molecular patterns and immunosenescence, thereby increasing morbidity and mortality." (PMID 37372149, 2023).
Obesity (continued). "Several preclinical studies in the past attempted to investigate the relationship between obesity and associated IR possibly mediated by TNF-α." (PMID 37239098, 2023). "The obesity-associated inflammatory cytokines, TNF-α, INF-γ, and leptin, increase VEGF-A levels and affect angiogenesis in MDA-MB-231 cells." (PMID 36880535, 2023). "Obesity causes chronic low-grade systemic inflammation that releases TNF-α and leads to insulin resistance, which further enhances adipogenesis and lipid accumulation." (PMID 37367060, 2023). "Low SHBG levels seen in obesity are caused by the high lipid content of the liver and by high pro-inflammatory cytokines (TNF-α and IL-1)." (PMID 36767197, 2023). "Studies have determined that increased TNF expression can be linked to obesity by its tendency to function as a mediator of insulin resistance." (PMID 37899888, 2023). "Decreased insulin sensitivity correlates with immune modifications during pregnancy, such as increased circulating TNF-alpha and IL-6, which are believed to trigger obesity-associated metabolic inflammation." (PMID 37515062, 2023). "Although TNF is a classical pro-inflammatory cytokine, it is also found to be produced from adipose tissue, and associated to obesity-associated metabolic disease." (PMID 37563567, 2023). "In skeletal muscle, increased collagen deposition is associated with increased gene expression of TNF-α and F4/80, a macrophage infiltration marker, in obesity and insulin resistance." (PMID 37383542, 2023). "Further integrated bioinformatics and meta-analysis of multi-omics data and clinical evidence points to interconnected inflammatory and immune dysfunction centered around AKT1, IL-6, and TNF as key mechanisms linking obesity to elevated gastric cancer risk." (PMID 37954072, 2023). "Elevated maternal TNF-alpha has been linked to obesity, preterm delivery, and hyperlipidemia, while elevated TNF-alpha from preterm kids' cord blood has been linked to cognitive deficiencies at five years of age." (PMID 38111393, 2023). "The main adipokines associated with development of obesity are leptin, adiponectin, resistin, TNF-alpha, and IL-6." (PMID 37629396, 2023). "Exemplifying the role of these pro-inflammatory factors in the pathogenesis of T2D is a mouse model of diet-induced obesity, where inhibition of Tumor necrosis factor alpha (TNFα) prevents the onset of obesity-associated insulin resistance." (PMID 37175908, 2023). "Obesity and presence of adipose tissue have also been linked to increased amounts of inflammation in the body, and not only increase tumor necrosis factor (TNF) but also markers like C‐reactive protein (CRP) and interleukin." (PMID 36635080, 2023). "Low-grade obesity-induced inflammation leads to the generation of IL-6 and TNF-α with tumor-promoting effects, activating tumor-associated neutrophils and macrophages." (PMID 37834153, 2023). "Now, it is the general consensus that obesity predisposes to a pro-inflammatory state with increased inflammatory mediators such as IL-6 and tumor necrosis factor alpha (TNF-α)." (PMID 37106699, 2023). "Circulating endotoxins have been associated with increments of cytokines such as TNF-α and IL-6 in adipocytes and, accordingly, subclinal levels of LPS, have been linked with high-fat diets, obesity, and other metabolic disorders." (PMID 36786619, 2023). "In mice with obesity-associated asthma, TNF-α increases metalloproteinase (MMP)-9 and in situ gelatinase activity and contributes to airway remodeling." (PMID 37377958, 2023). "The liver is chronically exposed to TNF-α and IL-6, the two major obesity-associated adipose-derived pro-inflammatory cytokines." (PMID 38313077, 2023). "As a risk factor, obesity predisposes to a pro-inflammatory state through an increase in inflammatory mediators such as IL-6, TNF-α or HGBM-1." (PMID 36596839, 2023).
Obesity (continued). "Pro-inflammatory cytokines that are associated with obesity and aging include tumor necrosis factor α (TNF-α), interleukin 6 (IL-6), and C-reactive protein (CRP), which cause peripheral blood mononuclear cells to be in a pro-inflammatory state." (PMID 37372149, 2023). "Obesity is a chronic inflammatory disorder in which necrotic adipocytes attract inflammatory cells and release inflammatory cytokines like TNF-α; PCOS is also associated with higher levels of M1 macrophages and inflammatory cytokines like TNF-α and IL-6." (PMID 37215125, 2023). "IL-1β, IL-6, and TNF-α are classical pro-inflammatory cytokines associated aging and obesity, the levels of IL-1β, IL-6, and TNF-α in serum were significantly decreased in the Y-ASC transplantation group when compared to the old control group." (PMID 37533129, 2023). "The inflammation caused by insulin resistance can be identified by the increasing level of the serums TNF-α, IL-2, and IL-6 in the M group, indicating the inflammatory response is caused by obesity." (PMID 37569125, 2023). "Overexpression of TNF-α causes more adverse complications in COVID-19 patients with comorbidities such as hypertension, obesity, and cardiovascular diseases (CVD)." (PMID 37047115, 2023). "The subacute inflammatory state associated with obesity is believed to be induced and sustained by pro-inflammatory and anti-inflammatory cytokines, such as TNF-α, IL-6, and resistin." (PMID 37241120, 2023). "Elevated levels of TNF‐α are considered a signature characteristic and key driver of the inflammation associated with obesity and NAFLD." (PMID 38107091, 2023). "Chronic inflammation caused by obesity leads to increased secretion of tumor necrosis factor-α (TNF-α), IL-6, IL-18, and other Th1 cytokines that can also inhibit adiponectin." (PMID 37266440, 2023). "From this review, the association between obesity and TNF-α levels during the periconceptional period remains controversial, with the majority of studies not showing a relationship." (PMID 36520252, 2023). "Mice lacking the IL-22 receptor are more susceptible to HFD-induced obesity and IR, and treatment of obese mice with IL-22 suppresses TNF expression in adipose tissue, as well as improving IR." (PMID 39872860, 2023). "Obesity is a cause of chronic low-grade inflammation, which leads to a marked elevation of acute-phase proteins and inflammatory cytokines, such as TNF-α." (PMID 36208911, 2023). "The cause of obesity and metabolic syndrome can be attributed to the methylation process affecting known as insulin-like growth factor 2 (IGF2) gene and the hypermethylation of two obesity-associated genes, leptin and tumor necrosis factor (TNF)." (PMID 38248733, 2023). "Obesity-associated pro-inflammatory molecules (e.g., TNFα, FFAs, Resistin, AGEs, and CCL-2) can cross the BBB, propelling hypothalamic inflammation." (PMID 36829858, 2023). "During the last decade, several studies have suggested that obesity is associated with an inflammatory process characterized by increased plasma levels of proinflammatory cytokines such as TNF-α, IL-6, and C-reactive protein." (PMID 36902133, 2023). "The causal role of TNF-α generating anxiety behavior due to bad nutritional state was proven in a genetic mouse model of obesity, db/db mice." (PMID 37373230, 2023). "As obesity is always associated with chronic inflammation and oxidative stress, we also detected the levels of tumor necrosis factor-alpha (TNFα) and malondialdehyde (MDA) in the plasma." (PMID 37511356, 2023). "Obesity is associated with chronic low-grade inflammation immune conditions and is usually accompanied by elevated pro-inflammatory cytokine levels such as TNF-α." (PMID 35990345, 2022). "Dysregulated adipocytokines and adipokines in obesity, such as leptin, resistin, TNF, and IL-6, are associated with the vascular dysfunction process." (PMID 35883829, 2022).